TNF (tumor necrosis factor)
Diseases named in the same sentence as TNF in open-access papers (continued):
Sharing a sentence is not in itself a finding about the gene and the disease.
Obesity (continued). "Other studies showed that circulating levels of amyloid A protein, interferon-gamma (IFN-γ), interleukin-6 (IL-6), tumor necrosis factor alpha (TNF-α), and C-reactive protein (CRP) were prominently reduced in patients with obesity by CR." (PMID 37755259, 2023). "During obesity, adipose tissue macrophages (ATM) are polarized into pro-inflammatory M1-like macrophages and secrete many pro-inflammatory cytokines, such as TNF, capable of impairing insulin signalling, therefore, promoting the progression of IR." (PMID 36175539, 2023). "Therefore, we suggest that, besides TNF-α, there should be other factors in the group with obesity involved in insulin resistance, like high levels of leptin, along with low levels of adiponectin and IL-10, which may interfere with inflammation control and insulin sensitivity." (PMID 37215211, 2023). "For example, curcumin prevents obesity-related colorectal cancer by attenuating chronic inflammation and improving adipokine imbalance, reducing cyclooxygenase-2 (COX-2), AMPK, NF-κB, TNFα, IL-6 and leptin levels, while increasing adiponectin levels." (PMID 36670988, 2023). "All together, these results suggest that TNF-α acts as a link between insulin resistance and enhanced PAI-1 in obesity." (PMID 37514235, 2023). "Supplementation with vitamin D3 decreased the production of proinflammatory cytokines: TNFα, PAI-1 (plasminogen activator inhibitor-1), IL-6, and ROS and pro-fibrotic genes in studies on AT biopsies from patients with obesity and 25(OH)D insufficiency." (PMID 38276294, 2023). "Obesity and MetS could promote BC proliferation, invasion and progression through low chronic inflammation and imbalance of tumor microenvironment which result in increased production of fibroblasts, T cells and pro-inflammatory cytokines such as TNF-a, IL-6, and IL-8." (PMID 38040773, 2023). "Individuals with obesity display a two to three-fold increase in circulating levels of C-reactive protein (CRP), tumor necrosis factor-alpha (TNF-alpha), and interleukin-6 (IL-6), when compared to their normal weight counterparts." (PMID 37139450, 2023). "TLR-4 activation further stimulates the IKB kinase/nuclear factor kB (NF-kB) pathway, causing the production of proinflammatory cytokines, such as IL-6, IL-8, TNF, and IL1 (Hypothalamic Inflammation and Obesity: A Mechanistic Review)." (PMID 37764744, 2023). "For instance, microglial activation increased TNFα secretion, leading to mitochondrial stress and altered firing rates in adjacent POMC neurons, thus contributing to the development of obesity in mice." (PMID 37720534, 2023). "The secretion of inflammatory cytokines such as tumor necrosis factor-α (TNF-α) and interleukin 6 (IL-6) by adipocytes is increased in obesity-induced adipose tissue inflammation." (PMID 37892415, 2023). "Interleukin-6 (IL-6) and tumor necrosis factor-alpha (TNF-α) are cytokines activated by pro-inflammatory signaling pathways in adipose tissue macrophages and are elevated in obesity." (PMID 37299403, 2023). "We have also analyzed the relationships between plasma concentrations of sP2X7R and the most common plasmatic inflammatory markers associated with the chronic low-grade inflammation present in obesity, such as CRP, TNFα and IL-6." (PMID 38069064, 2023). "In conclusion, our meta-analysis demonstrated the beneficial effect of ALA supplementation on reducing CRP, TNF-α, SBP, and TG in individuals with obesity or overweight." (PMID 37778442, 2023). "The strength of our study is expressed when examining the relationship between selected measures of obesity (BMI, WC, RFM, VAI, WHtR) and parameters of chronic inflammation (CRP, TNF-α, IL-6) in perimenopausal healthy women." (PMID 37375693, 2023). "The reduction in TNF-α levels is particularly noteworthy, as TNF-α plays a significant role in obesity-related insulin resistance and metabolic dysfunction." (PMID 37571229, 2023).
Obesity (continued). "Obesity in SLE increases the expression of interleukin 23 (IL-23), tumor necrosis factor alpha (TNF-α), IL-6, and C-reactive protein (CRP)." (PMID 36839394, 2023). "Instead, decreases in BMI, TNF-α, IL-6, and CRP, most of them significant, were reported in the reports by Moore on the population with overweight or obesity." (PMID 37885010, 2023). "Several studies have verified that the TNF-α level was higher in the serum and follicular fluid (when collected at oocyte retrieval) of women with simple obesity and PCOS patients with obesity." (PMID 37427330, 2023). "Further, a VLCKD improves inflammation, reducing TNF-alpha, PAI-1, IL-6, IL-8 and MCP-1, which are strongly involved in the pathophysiology of cardiovascular diseases and obesity." (PMID 37960300, 2023). "In light of the potent anti-inflammatory actions described for MaR1 on adipose tissue in obesity, we also evaluated the ability of this SPM to counteract the alterations induced by TNF-α on adipokines expression/secretion." (PMID 37371501, 2023). "In summary, moderate intensity walking is an effective therapeutic expected improving percent body fat, TNF- and hs CRP in postmenopausal women with obesity." (PMID 37978254, 2023). "It is being used to observe how this particular EVOO component reverses inflammatory parameters (elevated TNF-, IL-1, and IL-6) and inhibits the activation of TLR-4 and NK-kB pathways, which are related to intestinal permeability in obesity." (PMID 36837428, 2023). "Due to adipose tissue dysfunction in states of obesity, WAT predominantly expresses proinflammatory adipokines and cytokines, such as Il-1b, Il-6, Il-12, TNF-α or interferon gamma, which contribute to the conditions of chronic systemic inflammation in obesity." (PMID 37239098, 2023). "The release of inflammatory chemicals from adipose tissues, such as tumor necrosis factor-alpha (TNF-α), interleukin (IL)-6, and leptin, contribute to chronic inflammation in the context of obesity." (PMID 37503494, 2023). "Adipose macrophages produce cytokines such as interleukin-6 (IL-6) and tumour necrosis factor-alpha (TNF-α) which exacerbate the inflammatory response to SARS-CoV-2 infection and lead to severe COVID-19 in individuals with obesity." (PMID 37254139, 2023). "Gene expression of leptin, PAI-1, and tumor necrosis factor-α was lower in ABD than FEM SAT and higher in women with obesity than normal weight." (PMID 37455922, 2023). "Like TNF-α, IL-6 is related to the progression from steatosis to HCC, and its increased levels in obesity is related to several ways." (PMID 37266440, 2023). "In obesity, PI3K-AKT (FC 2.76, 95% CI: 0.87-4.65), inflammatory cytokines (FC 2.60, 95% CI: 1.61-3.59), and TNF signaling (FC 1.29, 95% CI: 0.75-1.62) were upregulated." (PMID 37954072, 2023). "In contrast, MAIT cells in obesity induced M1 polarization of macrophages in an MR1-dependent manner, thereby promoting inflammation with high TNF production and metabolic dysfunction." (PMID 36875139, 2023). "Obesity and HFD augmented the expression of the TNF-α pro-inflammatory gene and reduced the expression of anti-inflammatory (IL-10) genes." (PMID 38116571, 2023). "After feeding high-fat and high-sucrose diets mixed with Hericium erinaceus mycelium (HEM) or EA for 18 weeks, lowering hippocampal messenger RNA (mRNA) expressions of TNF-α and IL-1β, HEM and EA limit the progression of obesity-induced neurodegeneration." (PMID 36675019, 2023). "Paralleling this remodeling of adipose tissue, we found that leptin, resistin, glucagon-like peptide-1 (GLP-1), glucagon, TNF-α, and IL-6 were elevated in serum from DIO-HFD mice relative to CON-LFD, and DIO-VSG suppressed this obesity-driven increase." (PMID 37698918, 2023). "Increased circulating pro-inflammatory cytokines and adipokines (e.g. TNF-α, leptin, resistin, plasminogen activator inhibitor-1, CRP, IL-1β and IL-6) contribute to systemic inflammation in obesity but are also established predictors of cognitive impairment." (PMID 37086380, 2023).
Obesity (continued). "CD4+ T cells contribute to the inflammatory state in both, HF and obesity, and promote the generation of effector CD8+ T cells, for example, via enhanced antigen presenting cell-mediated IL-6 and TNF-α production." (PMID 37885885, 2023). "The enhanced TNF production by dendritic cells following BAC administration, in response to LPS, also positions BAC as a potential adjunctive therapy in obesity management." (PMID 38203609, 2023). "After lean and obese Zucker rats were fed a casein control diet, SPC-LIF diet, or SPC-HIF diet for 18 weeks, liver TNF-α, MCP-1, iNOS, and LBP expression levels had significant interactions between diet and obesity status." (PMID 38075211, 2023). "Obesity:- ↓ Plasma glucose triglyceride, and cholesterol concentrations.- ↑ GLP-1.Immunomodulation:- ↓ TNF-α." (PMID 37954670, 2023). "The levels of other inflammatory cytokines, such as TNFα, MCP-1, IL-1β, and IL-8, also tend to increase in obesity." (PMID 37892420, 2023). "In adipose tissue, the DNMT3a methyltransferase was markedly increased which was accompanied by elevated expression of inflammatory cytokines such as TNFα and MCP-1, implying the role of DNMT3a in obesity related inflammation." (PMID 36979493, 2023). "After activation of macrophages, levels of TNF-α, IL-6, and RANTES elevated during obesity maintain homeostatic control of AT mass." (PMID 35456006, 2022). "Purified sweet cherry anthocyanins at 200 mg/kg in mice reduced body weight by approximately 11.2% and decreased the expression of the IL-6 and TNF-α genes in white adipose tissue (WAT), slowing down the progression of obesity in these mice." (PMID 35740977, 2022). "In the MC38 model, obesity led to a reduction in IFN-γ+, double-expressing IFN-γ+TNF+, and GzmB+ CD8 T cells." (PMID 35103755, 2022). "This analysis highlighted an increase in pro-inflammatory cytokines TNF-α and IL-6 and upregulation of NF-κB-related genes NFKB1 and RELA in obesity." (PMID 35215414, 2022). "In the animal model of obesity, the occurrence of CLS is related to the activation of NF-κB, and the increase in inflammatory mediators (such as TNF-α and IL-1β) is closely related to NETs and METs." (PMID 35036449, 2022). "In fact, in endometria from women with obesity and PCOS, increased levels of molecules related to the tumor necrosis factor-alpha (TNFα) signaling pathway, which is considered to be an obesity marker and negative regulator of insulin action, can be observed." (PMID 35409282, 2022). "Consistent with the heightened activation of PRRs, ELISA showed that serum cytokine concentrations of TNF-α, IFN-γ, IL-1β, IL-6, and IL-17A were significantly induced with obesity, as was anti-inflammatory TGF-β and IL-10." (PMID 36406423, 2022). "Furthermore, obesity promotes the initiation of numerous pro-inflammatory pathways by causing TLR4-mediated inflammatory responses that involve activation of the transcription factor NF-κB and the production of pro-inflammatory mediators such as IL-6, IL-1, and TNF-α." (PMID 35740977, 2022). "In humans, TNF-α levels are elevated in people with T2DM and obesity, and TNF-α itself plays roles in the development of insulin resistance." (PMID 36248900, 2022). "For example, in obesity, IL-6 acts as a Th2 cytokine by stimulating M2 polarization and local ATM proliferation, whereas Th1 cytokines such as TNF-α inhibit local ATM proliferation." (PMID 35468098, 2022). "For MCP-1, TNF-α and VEGF, the reduction in concentration after treatment with Metformin was only observed in women with grade III obesity, suggesting that these changes depend on the degree of obesity." (PMID 35413055, 2022). "Recent studies also show that TNF-α, IL-6, and IL-1 promote IR, with TNF-α level as the main link between obesity and IR." (PMID 35956404, 2022). "The low-grade chronic inflammation state in obesity is also responsible for impairment in skeletal muscle glucose uptake by activating TLR-4 and TNF-α." (PMID 35683979, 2022).
Obesity (continued). "The increased production of cytokines such as tumor necrosis factor (TNF)-α released by these immune cells further impairs metabolism and other aspects during obesity, resulting in metabolic organ dysfunction." (PMID 36517853, 2022). "The pro-inflammatory cytokines TNF-α and IL-6 stimulate PAI-1 expression in human AT and adipocytes via NF-κB activation, suggesting a close relationship between PAI-1 and obesity-induced inflammation." (PMID 35909571, 2022). "Proinflammatory cytokines—such as interleukin (IL)-8, tumor necrosis factor-alpha (TNF-α) and other proteins as C-reactive protein (CRP)—are increased in cardiovascular disease (CVD), type II diabetes and obesity." (PMID 35529460, 2022). "In our study, the results of ELISA illustrated the effects of exercise on TNF-α, IL-1β, and IL-10 levels in the serum of mice with HFD-induced obesity." (PMID 36145106, 2022). "Adipose cells secrete approximately 50 exclusive cytokines, chemokines, and hormonal elements including IL-6, IL-8, IL-1β, tumor necrosis factor (TNF)-α, VEGF, CCL2, CCL5, and MMP9, which can also make a contribution to obesity and TME." (PMID 35205204, 2022). "Many studies have found that the roles of inflammatory adipokines such as TNFα, IL6, and IL1β in obesity-related diseases are attributed to altered miRNA profiles." (PMID 36421371, 2022). "The relationship between TNFα and ADAM17 levels and obesity is important because ADAM17 is responsible for the biological activity of TNFα." (PMID 36286024, 2022). "Because we were focusing on inflammatory cytokines that play a major role in developing obesity, we quantified the level of IL-1β, IL-6, IL-17A, IFN-γ and TNF-α in the plasma of lean, HFD and GaELNs treated HFD mice." (PMID 35154484, 2022). "The knockdown of TNFα downstream signals in the mediobasal hypothalamus reverses mitochondrial dysfunction and reduces body weight in high-fat diet (HFD)-induced obesity." (PMID 39871928, 2022). "In obesity, adipose tissue produces cytokines such as interleukin (specifically IL1ß and IL6), interferon γ (IFNγ), Tumor Necrosis Factor α (TNFα), and Monocyte Chemoattractant Protein 1 (MCP1), which promote chronic inflammation." (PMID 36009143, 2022). "Since AMPK is a crucial molecule in obesity, most studies in this review showed an elevated expression of AMPK, decreasing p-SREBP1-c, p-ACC, CPT-1, and TNF-α." (PMID 35893900, 2022). "In states of obesity, as the PVAT mass increases, the contractile and the proinflammatory cytokine TNFα increase, whereas anticontractile factors significantly decrease." (PMID 36145220, 2022). "Microglial cells are one of the major immune cells releasing IL-1β, TNF-α and IFN-γ which plays a critical role in brain inflammation in high-fat diet induced obesity." (PMID 35154484, 2022). "Another aspect of obesity and T2DM is the increase in the serum levels of inflammatory cytokines such as interleukin-6 (IL-6) and tumor necrosis factor-alpha (TNF-α)." (PMID 36355818, 2022). "Previous studies reported that DPP4 inhibitors could ameliorate high-fat diet-mediated obesity-related glomerulopathy, which may relate to the improved insulin sensitivity and reduced local inflammation through inhibiting macrophage infiltration and IL-6 and TNF-α secretion." (PMID 35935760, 2022). "Activated C-Jun transcription factors bind to AP-1 sites, thereby promoting the expression of pro-inflammatory factors (e.g., TNFα, IL1β, IL6, etc.), which play a key role in impaired glucose tolerance and insulin resistance by HFD-induced obesity." (PMID 35715850, 2022). "Elevated plasma levels of C-reactive protein (CRP) and pro-inflammatory cytokines such as IL-6, TNF-α, MCP-1, IL-8, and IL-7 confirmed the existence of an inflammatory state in individuals with obesity." (PMID 35896710, 2022). "Obesity, by inducing local hypoxia in the enlarged, VAT, stimulates sustained release of pro-inflammatory mediators (e.g., TNFα) from resident adipose tissue macrophages." (PMID 35328666, 2022).
Obesity (continued). "Increased free fatty acids and TNF-α from adipocytes and ATMs activate NF-κB and JNK signaling pathways, mediating obesity-induced insulin resistance and lipid accumulation in the liver." (PMID 35052852, 2022). "Interestingly, obesity is characterized by excess fat accumulation in white adipose tissue, in which inflammation is activated through the secretion of pro-inflammatory factors such as IL-6, IL-12, and TNFα, and transcription is activated via the NF-κB activation pathway." (PMID 35326476, 2022). "Secretion of TNFα, IL-6, and MCP-1 from both myocytes and skeletal muscle are increased in chronic conditions such as obesity and have been shown to contribute to impaired glucose uptake and insulin resistance." (PMID 35889783, 2022). "Obesity-induced inflammation is mostly triggered by the TLR4 signaling pathways, and it leads to the production of TNF-α pro-inflammatory cytokines." (PMID 36360622, 2022). "HFD-induced obesity increases the number of ILC1s and induces them to produce IFN-γ and TNFα in the visceral adipose tissue (VAT), then ILC1s-derived IFN-γ and TNFα accelerate M1 macrophages accumulation and promote insulin resistance." (PMID 36230963, 2022). "Lactobacillus casei CRL431 administration decreased inflammatory cytokines, includingIL-6, TNF-α, and MCP-1, in adipocytes and macrophages in diet-induced obesity." (PMID 35865314, 2022). "A controlled clinical trial evaluated the anti-inflammatory and antioxidative effects of OEA (250 mg/day) on obesity, as well as assessing LPO, TAC, CRP, IL-6, and TNF-α levels." (PMID 36120593, 2022). "The concentration of pro-inflammatory cytokines, TNF-α, in the blood is elevated in OSAS and obesity." (PMID 36430593, 2022). "The results showed that CIP decreased the serum levels of inflammatory cytokine TNF-α and the mRNA expression levels of IL-6, IL-1β, and TNF-α in mice, suggesting that CIP improved inflammation during the development of obesity." (PMID 36235584, 2022). "DCT prevented the obesity-induce upregulation of MCP-1 (p < 0.001) and IL-6 (p < 0.01) and DCTE also reduced the gene expression of TNF-α (p < 0.05)." (PMID 36139877, 2022). "Elevated concentrations of some inflammatory cytokines are seen in obesity, such as interleukin 4 (IL-4), monocyte chemoattractant protein 1 (MCP-1), IL-6, and TNF-α." (PMID 36295052, 2022). "CGA has been shown to reduce oxidative damage, control the inflammatory response through inhibition of TNF-α, IL-6, and IL-1β, increase insulin sensitivity, and prevent CVD and obesity through lipid metabolism modulation." (PMID 35683374, 2022). "The inflammatory factors, represented by interleukin-1β (IL-1β), interleukin-6 (IL-6) and tumor necrosis factor-α (TNF-α), are ultimately responsible for the inflammation in inflammatory bowel disease (IBD), obesity and other inflammation-related diseases." (PMID 35954128, 2022). "In mice, adipose tissue can be the source of tumor necrosis factor (TNF)-α, a cytokine which is increased in obesity and alters insulin sensitivity, indicating once again, a link between metabolic and inflammatory regulation." (PMID 36457996, 2022). "Studies have shown increased expression of inflammatory markers (i.e., TNF-α, IL-1β, and IL-6) by adipose tissue in mice with HFD-induced obesity." (PMID 35456900, 2022). "Children with obesity display increased MAIT cell frequencies (2.2% vs 2.8%, p=0.047), and, once activated, these produced elevated levels of both TNF-α (39% vs 28%, p=0.03) and IL-17 (1.25% vs 0.5%, p=0.008)." (PMID 35305128, 2022). "It is known that cytokines such as tumor necrosis factor-α (TNF-α) and monocyte chemoattractant protein-1 (MCP-1) in adipocytes are positively correlated with obesity." (PMID 35409375, 2022). "In individuals with class II obesity, additional WBC sessions affect body composition, proinflammatory TNF-alpha and LEP levels, and HDL/LDL ratio." (PMID 35203477, 2022).